ATF3 (activating transcription factor 3)
Diseases named in the same sentence as ATF3 in open-access papers (continued):
Sharing a sentence is not in itself a finding about the gene and the disease.
diabetic angiopathy (2 papers, 2013 to 2023). "In addition, ATF3 has been shown to potentially mediate diabetic angiopathy." (PMID 37189834, 2023).
endometrial carcinoma (2 papers, 2021). A malignant tumor arising from the epithelium that lines the cavity of the uterine body. "It has been reported that ATF3 overexpression impacted the proliferation, cell cycle, apoptosis, migration, and invasion of endometrial carcinoma, while estrogen and progesterone had a significant role in its pathogenesis." (PMID 33846304, 2021).
endotoxemia (2 papers, 2013 to 2025). "In this study, we demonstrated that ATF3 exhibited a protective effect against LPS- induced endotoxemia in mice." (PMID 24062788, 2013). "In LPS-induced mouse endotoxemia model, the survival rate was lower in atf3−/− group compared with control group but returned to near control level after transfection of AAV-ATF3 in atf3−/− mice." (PMID 24062788, 2013). "Although ATF3 expression is believed to play an important role in response to various stresses, little is known about its function in endotoxemia." (PMID 24062788, 2013). "We found that ATF3 protects against LPS-induced endotoxemia in mice through reducing HMGB1 expression." (PMID 24062788, 2013). "We further demonstrated that ATF3 gene knockout in mice subjected to LPS-induced endotoxemia correlates with an increase in the mortality rate and the elevated expression of IL-6, TNF-α, NO, MCP-1, and HMGB1 in the lung tissues or serum." (PMID 24062788, 2013). "However, it is unclear whether ATF3 plays a role in the HMGB1 regulation of LPS-induced endotoxemia." (PMID 24062788, 2013). "Therefore, we hypothesized that ATF3 may modulate the expression of IL-6 and TNF-α in the early and later stages of endotoxemia." (PMID 24062788, 2013).
fungal infection (2 papers, 2020 to 2021). "Loss of ATF3 in mice protects against bacterial and fungal infections under reactive oxygen species (ROS) stress." (PMID 32922364, 2020). "The relationships of ATF3 and ROS have been investigated; for example, the loss of ROS scavenger correlated to ATF3 upregulation, and ATF3 deficiency could against bacterial and fungal infection even under ROS stress." (PMID 34172832, 2021). "In contrast to these works, however, some studies indicate that ATF3 acts as a positive regulator for murine cytomegalovirus (MCMV) or bacterial and fungal infections." (PMID 32922364, 2020).
gram-positive bacterial infections (2 papers, 2018 to 2022). Infections caused by bacteria that retain the crystal violet stain (positive) when treated by the gram-staining method. "In contrast, in Gram-positive bacterial infections, ATF3 acted as a positive regulator to enhance the production of proinflammatory cytokines against pathogens such as Streptococcus pneumoniae, Listeria monocytogenes, and S. aureus." (PMID 35370996, 2022). "Activating transcription factor-3 (ATF3) in the ER stress pathway induces cytokine production and promotes survival during gram-positive bacterial infection." (PMID 30214444, 2018).
hematoma (2 papers, 2025). A hematoma is a collection of blood from a vascular structure into an extravascular space. "Among patients permitting dynamic sampling, both NIHSS scores and hematoma volume were profoundly positively relevant to serum ATF3 levels at serial time points post‐ICH (all P<0.001)." (PMID 41250979, 2025). "NIHSS scores in conjunction with hematoma volume are firmly correlated with serum ATF3 levels." (PMID 41250979, 2025). "Finally, to investigate whether increased ATF3 expression following ICH contributes to local neuronal damage within the hematoma, we conducted a series of experiments." (PMID 40680001, 2025). "In the context of ROC analysis, ATF3 levels at admission were in possession of an AUC, which was comparable to those of baseline NIHSS scores and hematoma volume." (PMID 41250979, 2025). "Dynamic serum ATF3 levels of patients consenting for serial sampling were firmly related to NIHSS scores, hematoma volume, SAP, END, continuous and ordinal mRS scores, and poor prognosis (mRS scores of 3–6)." (PMID 41250979, 2025). "Through receiver operating characteristic (ROC) curve analysis, admission serum ATF3 levels had predictive ability comparable to that of NIHSS scores and hematoma volume." (PMID 41250979, 2025). "For all patients, serum ATF3 levels at admission were tightly related to both NIHSS scores and hematoma volume (both p < 0.001)." (PMID 41250979, 2025). "Furthermore, for the sake of differentiating individuals with SAP from all patients, the AUC of admission serum ATF3 levels was not substantially different from those of NIHSS scores and hematoma volume (both p > 0.05)." (PMID 41250979, 2025).
Hypercholesterolemia (2 papers, 2012 to 2024). An increased concentration of cholesterol in the blood. "Consistent with these downward changes seen in hypercholesterolemia, expression of the ATF3 protein was induced in a time-dependent manner in both PrEC and LNCaP cells in response to cholesterol lowering in CDM." (PMID 22768301, 2012).
infarction (2 papers, 2023 to 2024). A localised pathological necrosis of tissue resulting from obstruction of the blood supply usually by a thrombus, an embolus, or vascular torsion. "In this study, we found the upregulation of the ferroptosis pathway geneset (derived from the KEGG hsa04216 and wikipathways WP4313) and ATF3 in infarction-stimulated cardiac cells (border zone, ischemic zone, and fibrotic zone), particularly the cardiomyocytes." (PMID 39070785, 2024).
insulinoma (2 papers, 2011 to 2019). "ER stress in insulinoma cells was shown to impair insulin signaling through activation of ATF3, an ER stress response protein that was implicated in suppression of IRS2 expression." (PMID 21541314, 2011). "al. demonstrating that high glucose and FFA together increased ATF3 mRNA expression, and that this was associated with increased apoptosis of insulinoma cells." (PMID 21541314, 2011). "al. when insulinoma cells and/or mouse islets were transfected with adenoviruses expressing inducible gain- or loss-of-function of ATF3 and IRS2." (PMID 21541314, 2011). "Treatments that induced ATF3 activation and IRS2 suppression included induction of apoptosis by combined treatment of insulinoma cells with γ-interferon, TNF-α, or the ER stress activator thapsigargin." (PMID 21541314, 2011). "A similar role for ATF3 in MIN6 and INS1 insulinoma cell stress response has been observed (Zmuda and Hai, unpublished observations)." (PMID 21541314, 2011).
intracerebral hemorrhage (2 papers, 2025). A cerebrovascular disorder characterized by bleeding into one or both cerebral hemispheres including the basal ganglia and the cerebral cortex. "Of note, the involvement of platelet activation in secondary brain injury following intracerebral hemorrhage (ICH) has been investigated; however, the regulatory mechanism of ATF3 in ICH remains unexamined." (PMID 40680001, 2025).
kidney (2 papers, 2023 to 2025). "While the specific role of ATF3 (activating transcription factor 3) in the suppression of PCa with PTEN (phosphatase and tensin homolog) dysfunction is meanwhile well known, the tumor suppressor function of IGF1, CXCL10, HIF1A, CXCL8, and CSF1 in prostate carcinogenesis remains to be elucidated." (PMID 36321189, 2023).
mantle cell lymphoma (2 papers, 2018 to 2023). Mantle cell lymphoma is a rare form of malignant non-Hodgkin lymphoma affecting B lymphocytes in the lymph nodes in a region called the ``mantle zone''. "It has been demonstrated that ATF3 and ATF4 physically associate and activate the Noxa promoter in mantle cell lymphoma cells." (PMID 29352505, 2018).
Mycoplasma pneumonia (2 papers, 2021 to 2025). "In addition, ATF3 facilitates the pathogen clearance in S. pneumoniae infection by promoting IL-17A production in γδ T cells, and it inhibits the secretion of inflammatory cytokines induced by Mycoplasma pneumonia in vitro and in vivo." (PMID 34135870, 2021). "Moreover, ATF3 can inhibit the release of inflammatory factors TNF‐α, IL‐1β, IL‐6, and IL‐18 induced by Mycoplasma pneumonia." (PMID 37385291, 2025).
oral squamous cell carcinoma (2 papers, 2013 to 2021). "Transgenic mice that over-express ATF3 in basal epithelial cells develop dysplastic lesions, epidermal hyperplasia, and oral squamous cell carcinoma." (PMID 24494067, 2013). "ATF3 has also been shown to play crucial roles in regulating tumor development and progression, however its potential role in oral squamous cell carcinomas has not been fully explored." (PMID 33539340, 2021).
pancreatic ductal adenocarcinoma (2 papers, 2020 to 2026). An infiltrating adenocarcinoma that arises from the epithelial cells of the pancreas. "But many key feature genes, such as TNFRSF14, XPO1, and ATF3, showed great promise on explaining perineural invasion in pancreatic ductal adenocarcinoma." (PMID 33193628, 2020). "The in-depth biological analysis of key feature genes, such as TNFRSF14, XPO1, and ATF3, shed light on the understanding of perineural invasion in pancreatic ductal adenocarcinoma." (PMID 33193628, 2020).
pancreatitis (2 papers, 2023 to 2024). Inflammation of the pancreas. "This allows for immediate transcriptional activation of YAP1 targets upon nuclear entry under stress conditions, consistent with previous observations that certain YAP1 binding partners, such as ATF3, can initiate transcriptional changes within hours of the onset of pancreatitis." (PMID 38247878, 2024). "Transcription activator factor 3 (ATF3) could activate the unfolded protein response (UPR) and promote the formation of ADM in pancreatitis in the presence of KRASG12D." (PMID 37152291, 2023).
retinal ischemia (2 papers, 2025). A ischemic disease that involves the retina. "ATF3 overexpression may be a potential therapeutic strategy for the management of retinal ischemia–reperfusion-associated neurodegenerative diseases." (PMID 41181154, 2025). "The potential neuroprotective mechanisms, function, and therapeutic potential of ATF3 following retinal ischemia–reperfusion remain largely unexplored." (PMID 41181154, 2025). "In central retinal artery ligation (CRAL)-induced retinal ischemia, ATF3 was reportedly activated 30 min post-CRAL and 3 h post-reperfusion." (PMID 41181154, 2025). "ATF3 overexpression improved retinal structure and function by regulating microglial behavior and decreased neuronal death post-retinal ischemia–reperfusion." (PMID 41181154, 2025). "ATF3 may be involved in the inflammatory communication between neurons and microglia during retinal ischemia." (PMID 41181154, 2025). "By contrast, our pathological model suggests that ATF3 does not contribute to the formation of pathological neovascularization due to retinal ischemia." (PMID 39790557, 2025).
Shock (2 papers, 2021 to 2022). The state in which profound and widespread reduction of effective tissue perfusion leads first to reversible, and then if prolonged, to irreversible cellular injury. "Upon induction, its gene product (ATF3 protein) reduces the expression of cytokine genes, which are also induced by septic shock." (PMID 34298975, 2021).
spinal cord injury (2 papers, 2020 to 2025). Penetrating and non-penetrating injuries to the spinal cord resulting from traumatic external forces (e.g., WOUNDS, GUNSHOT; WHIPLASH INJURIES; etc.).
T-cell leukemia (2 papers, 2011 to 2025). A malignant disease of the T-lymphocytes in the bone marrow, thymus, and/or blood. "For instance, ATF3 promotes adult T-cell leukemia cell proliferation by upregulating CDC2 and cyclin E217." (PMID 41453996, 2025).
Acidosis (1 paper, 2017). Abnormal acid accumulation or depletion of base. "Acidosis also increases the expression of several endoplasmic reticulum (ER) stress response genes such as CHOP (C/EBP homologous protein) and ATF3 (activating transcription factor 3)." (PMID 28134810, 2017).
adrenocortical cancer (1 paper, 2020). "Our studies suggest the possibility of interaction between NR5A1 and ATF3 associated with cell proliferation in adrenocortical cancer cells." (PMID 32093223, 2020).
Adult T-cell leukemia (1 paper, 2020). "Conversely, ATF3 could also promote proliferation of Adult T-cell leukemia (ATL) cells via mechanisms including upregulation of CDC2 and cyclin E2." (PMID 32398095, 2020).
airway hyperresponsiveness (1 paper, 2025). "What is more, ATF3 is a negative regulator of ovalbumin‐stimulated allergic inflammation in mice, and the lack of ATF3 induces airway hyperresponsiveness and increases pulmonary EOS in mice." (PMID 37385291, 2025).
allergic asthma (1 paper, 2020). A asthma with a basis in a pathological type I hypersensitivity reaction. "ATF3 is a known negative regulator of allergic asthma and was recently proposed to be a hub of the cellular adaptive-response network, playing a key role in immune diseases." (PMID 33095769, 2020).
Allergy (1 paper, 2012). An allergy is an immune response or reaction to substances that are usually not harmful. "ATF3 has also been shown to negatively regulate the transcription of pro-inflammatory cytokines and has important roles in the suppression of inflammatory responses to infection and allergy." (PMID 23028726, 2012).
anxiety disorder (1 paper, 2018). A category of psychiatric disorders which are characterized by anxious feelings or fear often accompanied by physical symptoms associated with anxiety. "Our results suggests that the ATF3-Gelsolin pathway controls the synaptic transmission of fear memory possibly through actin polymerization and maintains fear responses at an optimal level to prevent anxiety disorders." (PMID 29515366, 2018). "Lacking ATF3 gene may lead to enhanced fear response observed in patients affected with anxiety disorders including PTSD." (PMID 29515366, 2018).
aortic aneurysm (1 paper, 2025). A ruptured aneurysm located in the wall of the proximal portion of the descending aorta proceeding from the arch of the aorta. "Moreover, the absence of ATF3 not only exacerbates the formation of aortic aneurysms but also leads to aortic dissection in Ang II‐challenged mouse models." (PMID 39731276, 2025).
Arrhythmia (1 paper, 2013). Any cardiac rhythm other than the normal sinus rhythm. "In our embryonic-ATF3 expressing model, the newborn mice had enlargedatria, atrial fibrosis, hypertrophic markers expression, arrhythmia, and earlydeath." (PMID 23874609, 2013).
Ataxia (1 paper, 2022). Ataxia refers to impaired coordination of voluntary muscle movement. "These cells resist apoptosis (BCL6) and can boost DNA repair via increased ATF3, which stabilizes the major DNA damage kinase ataxia telangiectasia mutated." (PMID 35196078, 2022).
Candida infection (1 paper, 2022). "In Candida infection, the main role of ATF3 is to inhibit inflammation." (PMID 35314002, 2022).
carcinoma of the esophagus (1 paper, 2014). "We first examined the expression of ATF3 in the progression from normal epithelium to carcinoma of the esophagus by using immunohistochemical staining." (PMID 25149542, 2014).
cerebrovascular diseases (1 paper, 2021). "Some studies also show that suppressing the expression of ATF3 could improve the prognosis of cardiovascular and cerebrovascular diseases through reducing cell death." (PMID 34262953, 2021).
chronic myeloid leukemia (1 paper, 2025). "In chronic myeloid leukemia (CML), Gal-9-induced apoptosis depends on the intrinsic apoptotic pathway, activating ATF3 expression." (PMID 40134029, 2025).
Cockayne syndrome-B (1 paper, 2014). "TFII-I interacted with genes encoding for the heme-regulated eIF2α kinase HRI (EIF2AK1), the Cockayne syndrome-B (CS-B or ERCC6), heterochromatin protein 1 beta (Hp1 beta, CBX1) and TF ATF3." (PMID 24875474, 2014).
dementia (1 paper, 2026). Loss of intellectual abilities interfering with an individual's social and occupational functions. "Activating transcription factor 3 (ATF3) is one of the most important transcription factors that regulate local and systemic inflammation in multiple pathophysiological processes such as cardiovascular disease, dementia, and ischemia/reperfusion-induced damage." (PMID 41944912, 2026).
ductal carcinomas (1 paper, 2007). "In particular, transcription regulators (ATF3, PIGR), genes encoding proteins with cytokine and growth factor activity (PTN, CX3CL1) and genes encoding proteins involved in ion transport and metabolism (ATP1A2, MMP7) were downregulated in ductal carcinomas when compared with normal cells." (PMID 17389037, 2007).
dysplasia (1 paper, 2025). A usually neoplastic transformation of the cell, associated with altered architectural tissue patterns. "For instance, biomarkers such as IFI27 and ATF3 differentiated metaplasia from dysplasia with statistically significant p-values (p = 0.009 and p = 0.003, respectively), revealing their potential utility in dysplasia diagnosis." (PMID 40620772, 2025).
emphysema (1 paper, 2023). "We show that loss of Atf3 expression in the endothelium diminished the regenerative capacity of the distal lung, resulting in a persistent emphysema-like phenotype and decreasing the activity of several signaling pathways known to be important for angiogenesis while increasing cytokine expression." (PMID 37233732, 2023).
eosinophilia (1 paper, 2012). "Consequently, ATF3-deficient mice exhibit increased airway hypersensitivity including enhanced eosinophilia." (PMID 22768301, 2012).
erythema multiforme (1 paper, 2021). Erythema multiforme (EM) refers to a group ofhypersensitivity disorders characterized by symmetric red, patchy lesions, primarily on the arms and legs. "Previous studies have shown increased ATF3 gene expression in monolayer cultures of skin KCs in response to chemical insult and UVR, and increased protein levels have been observed in the epidermis of patients with the inflammatory skin disease erythema multiforme." (PMID 34909715, 2021).
estrogen-receptor positive breast cancer (1 paper, 2022). "Analyses of The Cancer Genome Atlas data indicated that higher ATF3, FOS, and FOSB expression levels correlated with low HSF1 levels in estrogen receptor-positive breast cancer, reflecting higher heat shock-induced expression of these genes in HSF1-deficient MCF7 cells observed in vitro." (PMID 36010586, 2022).
Ewing sarcoma (1 paper, 2025). A small round cell tumor that lacks morphologic, immunohistochemical, and electron microscopic evidence of neuroectodermal differentiation. "In Ewing sarcoma, ATF3 positively mediates PI3K/AKT/mTOR signaling, which was identified as differentially enriched between and Ptf1acreERT/+KRASG12D/+ and APK organoids." (PMID 41198649, 2025). "In Ewing sarcoma, ATF3 promotes expression of chemokines that stimulate an M2 macrophage phenotype." (PMID 41198649, 2025).
familial amyotrophic lateral sclerosis (1 paper, 2011). An instance of amyotrophic lateral sclerosis that is caused by an inherited modification of the individual's genome. "However, ATF3 has also been shown to promote cell death by mediating the apoptotic effects of p38 MAPK, and its expression preceded the death of spinal motor neurons and correlated with phosphorylation of c-Jun in a mouse model of familial amyotrophic laterals sclerosis." (PMID 21249202, 2011).